SLC7A8 (solute carrier family 7 member 8)
Diseases named in the same sentence as SLC7A8 in open-access papers (continued):
Sharing a sentence is not in itself a finding about the gene and the disease.
diabetes (1 paper, 2022). "Of note, dysfunctional SLC7A8 has been associated with formation of cataract, a relatively frequent side effect in people with diabetes." (PMID 36364703, 2022). "It is also interesting to note that in elderly subjects the same allelic variants of SLC7A5-rs731710 and SLC7A8-rs3783436 were found associated with better physical performance, reported to be impaired in people with diabetes." (PMID 36364703, 2022). "In this respect, the marginal association of the allelic variants SLC7A5 rs731710-G and SLC7A8 rs3783436-C with a reduced risk of diabetes is a result that deserves some attention." (PMID 36364703, 2022).
diabetic eye disease (1 paper, 2022). A group of disorders affecting the eye in patients with diabetes mellitus. "Interestingly, we found the rs3783436 variant at SLC7A8 gene associated to a reduced risk of diabetic retinopathy, the most common diabetic eye disease leading cause of vision loss among adult people." (PMID 36364703, 2022).
diabetic retinopathy (1 paper, 2022). "Stratification of patients based on presence/absence of vascular complications highlighted significant associations of SLC7A8-rs3783436 and SLC38A7-rs9806843 with diabetic retinopathy." (PMID 36364703, 2022).
helminth infection (1 paper, 2023). "In line with our prior findings, we noted that while naive ILC2 had impaired surface CD98 expression in the absence of Slc7a8, they increased compensatory solute carrier expression upon activation by helminth infection." (PMID 36571761, 2023).
Hypertension (1 paper, 2024). The presence of chronic increased pressure in the systemic arterial system. "The association between SLC3A2 and SLC7A8 variants to hypertension development in patients with renal failure could be linked to changes in L-DOPA uptake and consequently dopamine synthesis." (PMID 38890684, 2024). "We examined the plausibility that SLC7A8/SLC3A2 gene polymorphisms may contribute to hypertensive CKD by affecting the L-DOPA uptake." (PMID 38890684, 2024). "A similar result was found for the marker of SLC7A8/LAT2 rs3783436-T/C, whose minor allele C resulted associated with reduced risk of hypertension when the G3 group was compared to the G4 in an additive model [OR = 0.56 (95% CI 0.35–0.90; p = 0.017]." (PMID 38890684, 2024). "It is difficult, however, to establish a clear correlation between dopamine levels, LAT2/4F2hc expression, and the risk of hypertension in the context of CKD, even in view of the pleiotropic effects that dopamine and the SLC7A8/SLC3A2 genes exert." (PMID 38890684, 2024). "A similar association with hypertensive CKD was found for the SLC7A8 (LAT2) rs3783436-T/C, whose C-allele resulted associated with decreased risk of hypertension among subjects affected by CKD [OR = 0.56 (95% CI 0.35–0.90; p = 0.017]." (PMID 38890684, 2024). "In conclusion, our preliminary findings derived from a hypothesis-driven candidate gene study offers suggestive evidence to support the role of SLC3A2 /SLC7A8 function to the development of hypertension in patients with renal failure." (PMID 38890684, 2024). "However, to our knowledge, no studies to date have examined the effect of genetic variants of SLC7A8 and SLC3A2 genes on the relationship between CKD and hypertension." (PMID 38890684, 2024).
leukoplakia (1 paper, 2024). A white patch or plaque on a mucous membrane that cannot be characterized clinically or pathologically as any other disease. "During the progression from leukoplakia to HNSCC, we found several prognostic cell subgroups, such as AURKB + epithelial cells, SFRP1 + fibroblasts, SLC7A8 + macrophages, FCER1A + CD1C + dendritic cells, and TRGC2 + NK/T cells." (PMID 38582791, 2024).
lung adenocarcinoma (1 paper, 2024). A carcinoma that arises from the lung and is characterized by the presence of malignant glandular epithelial cells. "However, the role of SLC7A8 in lung adenocarcinoma (LUAD) is still obscure." (PMID 38244585, 2024).
metabolic syndrome (1 paper, 2024). A cluster of metabolic risk factors for CARDIOVASCULAR DISEASES and TYPE 2 DIABETES MELLITUS. "Slc7a8, Pck1, Mgll, and Bhmt are associated with the regulation of metabolic homeostasis in the treatment of metabolic syndrome, and Fkbp5 plays a crucial role in the inflammatory response." (PMID 39126116, 2024).
muscular disease (1 paper, 2022). Myopathy is a peripheral nervous system disease consisting of any abnormal condition or disease of the muscular tissues; commonly designates a disorder involving skeletal muscle. "Hence, the decrease in lipid accumulation due to slc7a8 deletion in our study suggests an improvement in DIO-associated muscular disease." (PMID 35205177, 2022).
osteosarcoma (1 paper, 2022). A usually aggressive malignant bone-forming mesenchymal neoplasm, predominantly affecting adolescents and young adults. "In this study, we identified a novel locus in the SLC7A8 gene to be associated with EDP in patients with osteosarcoma." (PMID 36438828, 2022). "In our study we provided evidence that five genetic variants are associated with EDP in osteosarcoma, of which a locus in SLC7A8 was confirmed in an independent validation cohort." (PMID 36438828, 2022). "The association of a locus in the SLC7A8 gene to EDP may be caused by an interaction of LAT2 with chemotherapeutics that are used in the treatment of osteosarcoma." (PMID 36438828, 2022). "In combination with the association of LAT2 expression in tumor tissue with improved survival in patients without metastasis, LAT2-mediated doxorubicin transport could mechanistically explain the association of genetic variation in SLC7A8 that is associated with EDP in patients with osteosarcoma." (PMID 36438828, 2022). "Finally, SLC7A8 mRNA expression analysis and LAT2 immunohistochemistry of osteosarcoma tissue showed that the lack of LAT2 expression is a prognostic factor of poor prognosis and reduced overall survival in patients without metastases (p = 0.0099 and p = 0.14, resp)." (PMID 36438828, 2022).
steatosis (1 paper, 2022). Increased lipid within the cytoplasm of cells. "The observations made in our study indicated that KOHFD attenuated both the macrovesicular and the microvascular steatosis seen in WTHFD, suggesting that slc7a8 deletion could be protective against NAFLD in DIO." (PMID 35205177, 2022).
cancer (12 papers, 2020 to 2025). A tumor composed of atypical neoplastic, often pleomorphic cells that invade other tissues. "SLC7A8 regulates protein translation and cell proliferation through the mTORC1 pathway, enhancing glycolysis in several cancers." (PMID 41458991, 2025). "Specifically, we identified that SLC7A8 (LAT2) regulates the glutamine mechanism pathway involved in cancer progression." (PMID 38992159, 2024). "In contrast to most of the SLC transporters which have oncogenic function in cancer, SLC7A8 (LAT-2) was found to have dual functions." (PMID 38705513, 2024). "Glutamine is transported into cancer cells by the glutamine transporter, such as SLC7A8 and SLC7A5, or synthesize de novo in cancer cells." (PMID 37127605, 2023). "We estimated the cancer cell fraction of SLC7A8 p.T184P for each patient during the treatments, which was higher in PD patients (PD_P1_C3: 0.26, PD_P2_C3: 0.23) than in the PR patient (PR_P1_C2: 0.09)." (PMID 34494553, 2021). "Bioinformatics analyses showed that the expression levels of six out of 25 genes (ERO1B, DPY19L1, NCAM1, RET, MARCH1, and SLC7A8) were associated with LUAD patient survival (p < 0.05), and pathway analyses indicated that major cancer signaling was altered in the subtypes." (PMID 32235589, 2020). "The SLC36A1, SLC7A5, SLC7A8 genes, which are related to amino acid transmembrane transporter activity, could play a role in tumour uptake of amino acids produced by host protein degradation during cancer cachexia and contribute to the growth of tumors." (PMID 36428623, 2022). "Also, SLC1A4 and other transporters such as SLC7A8, SLC38A1, and SLC38A2 were detected as putative targets of an anti-cancer drug named Benzylserine in breast cancer, which their uptake activity is directly inhibited by this drug." (PMID 38705513, 2024). "Unlike SLC7A5, SLC7A8 lacks studies that illustrate its prognostic role in human cancer." (PMID 32200487, 2020).
tumor (12 papers, 2017 to 2025). "High expression of SLC7A8 mRNA and SLC7A8 protein was associated with good patient outcome (P ≤ 0.001) but only in the low proliferative ER+/luminal A tumours (P = 0.01)." (PMID 32200487, 2020). "Herein, we used large BC cohorts to reveal the significant associations between the high SLC7A8 expression, at mRNA and protein levels, and good prognostic clinicopathological parameters, including small tumour size, low tumour grade, and good NPI." (PMID 32200487, 2020). "High SLC7A8 mRNA expression was significantly associated with good prognostic parameters, including smaller tumour size (P = 0.007), lower tumour grade (P < 0.001), and good Nottingham Prognostic Index (NPI) (P < 0.001)." (PMID 32200487, 2020). "The associations between SLC7A8 and glutamine metabolic enzymes and transporters were primarily observed within luminal A tumours and to lesser extent in luminal B, HER2+ and TN subtypes." (PMID 32200487, 2020). "For example, luminal A tumours were the main class which showed association between SLC7A8 and markers required for glutamine transport and metabolism." (PMID 32200487, 2020). "In the METABRIC Integrative Clusters, high SLC7A8 mRNA expression was associated with clusters 7 and 8 which embrace ER+ tumours predominately of the luminal A intrinsic subtype (P < 0.001)." (PMID 32200487, 2020). "SLC7A8 mRNA and SLC7A8 protein expression were strongly associated with good prognostic features, including small tumour size, low tumour grade, and good Nottingham Prognostic Index (NPI) (all P < 0.05)." (PMID 32200487, 2020). "Furthermore, SLC7A8 mRNA and protein overexpression are associated with good prognostic features, including small tumor size, and low tumor-grade." (PMID 38705513, 2024). "We found that although MEPs expressed the four transporters, only SLC7A8 was upregulated in the MEPs of tumor-bearing mice." (PMID 37919525, 2023). "During tumor growth, large amounts of Kyn from tumor cells are released into the periphery, where they are taken up by MEPs via the transporter SLC7A8." (PMID 37919525, 2023). "Of note, the mRNA levels of Arg1, Slc7a8 and Slc7a11 were substantially higher in tumor than in splenic F4/80+ cells." (PMID 32396064, 2020). "While SLC7A8 mRNA expression was not predictive for BCSS in any specific molecular class, high expression of SLC7A8 protein was predictive of good survival in only the ER + low proliferation tumours (P = 0.01)." (PMID 32200487, 2020). "With respect to BC subtypes, the lowest levels of SLC7A8 mRNA were observed in the ER- and TNBC tumours, while SLC7A8 was higher in the ER+ subtypes which was more prominent in the luminal A tumours." (PMID 32200487, 2020). "This study has revealed, for the first time, that SLC7A8 is a key amino acid transporter in the most predominant low proliferative ER+ tumours." (PMID 32200487, 2020). "Cytokine IFN-γ secreted by T cell boosts the tumor-repopulating cells that exhibit high tumorigenicity and self-renews to release more kynurenine, which is transferred into T cells via SLC7A8 and PAT4 to increase PD-1 expression, accompanied by impaired anti-tumor immunity of T cells." (PMID 36231064, 2022). "Overexpression of SLC7A8 appears to have tumour suppressive characteristics especially in the low proliferative ER+ subtype, thus it could act as a potential prognostic factor." (PMID 32200487, 2020). "These statements indicate that SLC7A8 could be a key transporter in luminal A tumours through determining the actual net flux of not only the large but also the small neutral amino acids." (PMID 32200487, 2020). "Likewise, SLC7A8 mRNA was highly expressed in non-triple negative (TN) compared with TN tumours (P < 0.001)." (PMID 32200487, 2020). "Expression of SLC7A8 mRNA was higher in luminal tumours compared to other subtypes (P < 0.001)." (PMID 32200487, 2020).
tumor (continued). "Regarding the association of SLC7A8 CN and mRNA with the intrinsic (PAM50) subtypes, SLC7A8 CN gain was mainly observed in luminal B tumours (P < 0.001), whereas high mRNA expression was observed primarily in luminal A and B tumours and to lesser extent in HER2+BC (P < 0.001)." (PMID 32200487, 2020). "Further, we found that SLC7A8 + macrophages highly expressed CD163 and CD209 and other marker genes of M2 macrophages, which played a role in promoting tumor, inhibiting immune response, inducing angiogenesis and tissue repair." (PMID 38582791, 2024). "Multivariate Cox regression analysis showed that SLC7A8 mRNA and SLC7A8 protein were predictors of longer BCSS independent of tumour size, grade, and lymph node stage (P = 0.01 and P = 0.03) respectively." (PMID 32200487, 2020). "Although the result of the association of SLC7A8 protein in the defined IHC subtypes were not nominally significant, it also showed higher SLC7A8 expression in the ER+ low proliferation tumours compared with the other subtypes." (PMID 32200487, 2020). "Furthermore, we have shown that SLC7A8 was associated with better patient outcome and longer DMFS in the ER+ low proliferative tumours only and not in the other subtypes." (PMID 32200487, 2020).
cardiovascular diseases (1 paper, 2025). "The study reported that SLC7A8 may regulate cardiovascular diseases by influencing cellular functions through energy metabolism in cardiomyocytes." (PMID 40727388, 2025).
SLC7A8 also shares sentences with these, for which no sentence is quoted: colorectal cancer (2 papers); leiomyoma (2); leukaemia (2); allergic disease (1); allergic rhinitis (1); carotid atherosclerosis (1); esophageal cancer (1); folate deficiency (1); glioma (1); Glucose intolerance (1); head and neck carcinoma (1); invasive breast carcinoma (1); lung carcinoma (1); neurodegenerative disease (1); neurodevelopmental disorder (1); renal failure (1); Sepsis (1); Stroke (1).